NPEPPS (aminopeptidase puromycin sensitive)
Description:
Aminopeptidase with broad substrate specificity for several peptides. Involved in proteolytic events essential for cell growth and viability. May act as regulator of neuropeptide activity. Plays a role in the antigen-processing pathway for MHC class I molecules. Involved in the N-terminal trimming of cytotoxic T-cell epitope precursors. Digests the poly-Q peptides found in many cellular proteins. Digests tau from normal brain more efficiently than tau from Alzheimer disease brain.
Synonyms: PSA; AAP-S; MP100
Tractability: Small molecule: a drug acting on it is in phase 2 or 3 trials; a high-quality ligand is known. Antibody: its Gene Ontology location is reachable by antibodies, with medium confidence. PROTAC: ubiquitination databases record sites on it; its protein half-life has been measured; a small molecule that binds it is known.
Target class: Protease; Enzyme; Metallo protease; Metallo protease MAE clan; Metallo protease M1 family
Chemical probes: PD134331
Gene: Protein-coding gene on chromosome 17 (47,522,942 to 47,624,665, forward strand). Ensembl gene ENSG00000141279.
Subcellular location: Cytoplasm, cytosol; Nucleus
Subcellular location (Human Protein Atlas): Cytosol
Pathways (Reactome):
Immune System: Antigen processing: Ubiquitination & Proteasome degradation
Gene Ontology:
Molecular function: aminopeptidase activity; metalloaminopeptidase activity; alanyl aminopeptidase activity; metallopeptidase activity; zinc ion binding
Biological process: cellular response to hypoxia; positive regulation of establishment of protein localization to mitochondrion; peptide catabolic process; protein polyubiquitination; proteolysis
Cellular component: cytosol; extracellular exosome; extracellular region; cytoplasm; nucleus
Genetic constraint (gnomAD): Loss-of-function variants: 13 observed, 69.16 expected, observed/expected ratio (o/e) 0.19, 90% interval 0.12 to 0.3. The upper end of that interval is the gene's LOEUF score, 0.3, which puts it in group 1 of 6, group 1 being the genes least tolerant of losing a copy. Missense variants: 426 observed, 790.15 expected, observed/expected ratio (o/e) 0.54, 90% interval 0.5 to 0.58. Synonymous variants: 235 observed, 282.66 expected, observed/expected ratio (o/e) 0.83, 90% interval 0.75 to 0.93.
Homologues: Orthologues: macaque NPEPPS (99% identical), rabbit NPEPPS (99% identical), pig NPEPPS (99% identical), rat Npepps (98% identical), mouse Npepps (97% identical), guinea pig NPEPPS (91% identical), tropical clawed frog npepps (84% identical), zebrafish npepps (82% identical), chimpanzee NPEPPS (75% identical), Drosophila melanogaster Psa (53% identical), Caenorhabditis elegans pam-1 (37% identical). Paralogues in human: ERAP2 (32% identical), ERAP1 (32% identical), ENPEP (31% identical), ANPEP (31% identical), LNPEP (30% identical), LVRN (27% identical), TRHDE (24% identical), RNPEP (11% identical), LTA4H (11% identical), RNPEPL1 (11% identical), AOPEP (10% identical).
Diseases named in the same sentence as NPEPPS in open-access papers:
NPEPPS is named in the same sentence as 17 diseases in open-access papers, as found by Europe PMC text mining. Sharing a sentence is not in itself a finding about the gene and the disease. The quoted sentences say what the papers report.
pancreatic cancer (3 papers, 2012 to 2022). "Using multivariate Cox regression analysis, we detected eight optimal ubiquitination-related genes (RNF7, NPEPPS, NCCRP1, BRCA1, TRIM37, RNF25, CDC27, and UBE2H) and then used them to construct a risk model to predict the prognosis of pancreatic cancer patients." (PMID 33414811, 2020). "But we found that even though some genes (RNF7, NPEPPS, and NCCRP1) were down-regulated in tumor group, patients with pancreatic cancer with high expression of these genes had a worse prognosis." (PMID 33414811, 2020).
lung carcinoma (2 papers, 2018 to 2022). "In the lung cancer cell line PGCL3, miR-614 inhibited lung cancer cell invasion and proliferation by targeting the 3′ UTR of the NPEPPS gene." (PMID 29448950, 2018).
apocrine carcinoma (1 paper, 2024). "Of note, however, is the fact that one recently-published case of apocrine carcinoma carrying a RARA::NPEPPS fusion was found to be TRPS1-positive." (PMID 39449380, 2024).
autoimmune disease (1 paper, 2024). A disorder resulting from loss of function or tissue destruction of an organ or multiple organs, arising from humoral or cellular immune responses of the individual to their own tissue constituents. "In addition, NPEPPS is closely associated with various autoimmune diseases." (PMID 38464509, 2024).
breast carcinoma (1 paper, 2024). "For identification of PSA/NPEPPS expression in human breast cancers, KM Plotter database was used for overall survival analysis in gene (RNA-seq) and protein level." (PMID 38814491, 2024).
multiple sclerosis (1 paper, 2024). A progressive autoimmune disorder affecting the central nervous system resulting in demyelination. "This SNP is located in the region KPNB1‐DT, NPEPPS gene, which has been reported to be associated with multiple sclerosis." (PMID 38957036, 2024).
neuroblastoma (1 paper, 2011). Neuroblastoma (NB) is the most common solid, extracranial childhood tumor. "Our in vitro results with murine neuroblastoma cell line overexpressing SOD1 demonstrated an increase in PSA/NPEPPS protein expression." (PMID 21548977, 2011).
prostate carcinoma (1 paper, 2019). A carcinoma that arises from epithelial cells of the prostate gland. "From the literature data, we find that KLK3 and NPEPPS have been studied together in 52 articles in prostate cancer research in genetics among Finnish researchers." (PMID 30838019, 2019).
tumor (5 papers, 2012 to 2024). "Of the eight genes we identified, three genes (RNF7, NPEPPS, and NCCRP1) were down-regulated and the remaining five (BRCA1, TRIM37, RNF25, CDC27, and UBE2H) were up-regulated in tumor tissue compared to normal pancreatic tissue." (PMID 33414811, 2020). "Among the eight genes, five genes (BRCA1, TRIM37, RNF25, CDC27, and UBE2H) were significantly upregulated and three genes (RNF7, NPEPPS, and NCCRP1) were significantly down regulated in the tumor tissues." (PMID 33414811, 2020).
cancer (3 papers, 2021 to 2024). A tumor composed of atypical neoplastic, often pleomorphic cells that invade other tissues. "Here, we present a general mechanism where NPEPPS interacts with the volume-regulated anion channels (VRACs) to control cisplatin import into cells and thus regulate cisplatin response across a range of cancer types." (PMID 39671496, 2024). "In conclusion, this study unveils a previously unknown complexation event between NPEPPS and LRRC8A proteins, collectively establishing a compelling rationale for targeting NPEPPS to combat cisplatin resistance and enhance chemotherapy efficacy in cancer." (PMID 39671496, 2024). "Together, these data support NPEPPS as a stable, druggable target in treatment-resistant cancer." (PMID 39671496, 2024). "Of these, seven genes (BRIP1, ERCC4, FANCD2, FANCG, FANCI, MAD2L2, PPP2R2A) were previously related to the platinum sensitivity/resistance of different types of cancer cells, with NPEPPS being reported for the first time as a platinum drug sensitivity regulator." (PMID 35209078, 2022).
neurodegenerative disease (1 paper, 2020). A disorder of the central nervous system characterized by gradual and progressive loss of neural tissue and neurologic function. "It has not been reported that NPEPPS directly participates in the process of ubiquitination, but NPEPPS is also known to degrade the tau protein, which accumulates and polymerizes in some neurodegenerative diseases." (PMID 33414811, 2020).
NPEPPS also shares sentences with these, for which no sentence is quoted: tauopathies (2 papers); adenoma (1); amyotrophic lateral sclerosis (1); dementia (1); mild cognitive impairment (1); proteinopathies (1).